PFKFB3 (6-phosphofructo-2-kinase/fructose-2,6-biphosphatase 3)
Diseases named in the same sentence as PFKFB3 in open-access papers (continued):
Sharing a sentence is not in itself a finding about the gene and the disease.
tumor (continued). "As a regulator of glycolytic rate-limiting enzymes, PFKFB3 is a popular molecule in tumor-related research." (PMID 37509108, 2023). "The analysis of the pathway of PFKFB3 in pan-cancer can be used as a future reference for exploring clinical tumor therapy." (PMID 37253634, 2023). "We explored the relationship between PFKFB3 expression and the prognosis of different tumor patients." (PMID 37253634, 2023). "Significantly, the results of IHC staining also indicated the distinct difference of prognostic genes including SEPHS2, GPX7, and PFKFB3 between tumor and adjacent normal tissues." (PMID 37293295, 2023). "Increased glycolysis in tumor tip ECs is regulated by the glycolytic activators 6-phosphofructo-2-kinase/fructose-2,6-biphosphatase 3 (PFKFB3) and phosphofructokinase 1 (PFK1), which are important for cell migration and proliferation." (PMID 37025170, 2023). "A phase-1 dose escalation study for PFK-158, a first-in-human, first-in-class, small molecule inhibitor of PFKFB3, showed commendable tolerance and tumor burden reduction in pancreatic cancer, renal cell carcinoma, and adenocystic carcinoma patients." (PMID 36768924, 2023). "In further immunofluorescent staining of tumor tissues, we observed the binding of the antibody to the tumor cells, which confirmed the positive expression of PFKFB3 in all cell lines and cancer tissues used in this study." (PMID 37035116, 2023). "In fact, genetic ablation or pharmacologic inhibition of PFKFB3 can impair tip cell behavior and reduce sprouting, resulting in improved anti-cancer drug efficacy and decreased metastatic events in mouse tumor models." (PMID 37025170, 2023). "The CSC generated tumors with PFK158 treatment or knockdown of PFKFB3 significantly reduced tumor establishment as measured by vernier caliper and gradually inhibited tumor growth in dose dependent manner." (PMID 35804016, 2022). "PKM2 regulates mitosis, cell cytokinesis, homologous recombination repair, apoptosis, tumour cell exosomes and ectosomes, and PFKFB3 regulates DNA repair." (PMID 35429101, 2022). "Confocal microscopy demonstrated that PFKFB3-positive monocytes, that are precursors of TAMs, massively infiltrate tumor mass." (PMID 36733385, 2022). "PFKFB3 has been reported to be up-regulated and exhibit tumor-promotive roles in several types of malignant tumor." (PMID 35209949, 2022). "PFKFB3 inhibition/silencing indeed leads to a decrease in F-2,6-BP, subsequently reducing glycolysis and resulting in an inhibition of tumor growth and an induction of cancer cell death." (PMID 35865630, 2022). "As such, the inhibition of PFKFB3, and the subsequent decrease in F-2,6-BP, has been examined to determine its effects on tumor growth and cell death." (PMID 35865630, 2022). "Studies have found that 3PO, the specific inhibitor of PFKFB3, inhibits the production of lactic acid by glycolysis and inhibits tumor growth." (PMID 36589684, 2022). "Targeting PFKFB3 suppressed cancer cell proliferation in vitro and attenuated tumor growth or metastasis in animal models and radiosensitized cancer cells." (PMID 35454815, 2022). "Partial genetic or pharmacological inhibition of PFKFB3 was shown to normalize the tumor vasculature and reduce invasiveness in several tumor mouse models." (PMID 35664794, 2022). "As a vital regulator of glycolysis, 6-phosphofructo-2-kinase/fructose-2,6-bisphosphatase 3 (PFKFB3) was confirmed to have a higher expression level in tumor tissue and correlated with the prognosis of GC patients." (PMID 35094634, 2022). "Clinically, targeting LINC00930 and PFKFB3 in combination with radiotherapy induced tumor regression." (PMID 35209949, 2022). "Our prior work has shown that inhibition of PFKFB3 with the glycolytic inhibitor PFK158 attenuates tumor progression and increases the efficacy of conventional chemotherapy." (PMID 35804016, 2022).
tumor (continued). "In the tumor microvasculature, PFKFB3 haploid defects reduce the expression of EC adhesion molecules by reducing NF-κB signal transduction." (PMID 35418167, 2022). "PFKFB3 presents the highest kinase activity among the four isoforms and its inhibition resulted in the suppression of the growth of tumor cells by downregulating the glycolytic flux." (PMID 35433453, 2022). "Inhibition of PFKFB3 either genetically or pharmacologically normalized tumor blood vessels, leading to suppression of tumor metastasis and improvement of drug delivery." (PMID 36381236, 2022). "Up-regulation of PFKFB3 expression in nasopharyngeal and breast cancers promotes tumor cell proliferation, metastasis and angiogenesis." (PMID 35155224, 2022). "Autophagy and 6-phosphofructo-2-kinase/fructose-2,6-bisphosphatase 3 (PFKFB3) are both essential to the process of tumor progression, dormancy, and re-emergence." (PMID 36551290, 2022). "Knockout of PFKFB3 was conducive to improving chemotherapy response and weakening tumor invasion and metastasis by normalizing tumor blood vessels, particularly converting endothelial barrier dysfunction." (PMID 35784750, 2022). "Rapidly proliferating cancer cells constitutively express PFKFB3 in vitro, and inhibition of PFKFB3 expression decreases tumor growth in experimental animal models." (PMID 36733385, 2022). "In this study, we found that knockdown of PFKFB3 or inhibition by PFK158 was able to attenuate SCLC-CSC tumor cell migration/invasion." (PMID 35804016, 2022). "Due to its strong kinase activity, stabilized expression of PFKFB3 can elevate the rate of glycolysis, thereby promoting the blood vessel sprouting, affecting tumor angiogenesis." (PMID 36187335, 2022). "Recently, strong and growing evidence has highlighted the crucial role of PFKFB3 in tumor angiogenesis and metastasis." (PMID 35961977, 2022). "The molecular events of PFK158 or PFKFB3 knockdown exhibiting anti-pluripotency in CSC tumor were elucidated by performing western blot in randomly selected 6 tumors from each group." (PMID 35804016, 2022). "High PFKFB3 expression in cancer stem cells promotes glycolysis and survival in the tumor microenvironment." (PMID 35804016, 2022). "Inhibition with PFK158 or genetic knockdown of PFKFB3 showed reduced tumor formation in the CSC xenograft model with reduced expression of phospho-PFKFB3 S461 and total PFKFB3, and cancer stem cell markers including CD133, CD44, Aldh1, Sox2, and ABCG2." (PMID 35804016, 2022). "PFKFB3 is also involved in the regulation of glycolysis, cell viability, and proliferation in tumor cells." (PMID 36589684, 2022). "One of the critical role of PFKFB3 is to catalyze the conversion of F-6-P to F-2,6-BP, thus activating glycolysis and promoting tumor progression." (PMID 35209949, 2022). "Both the administration of PFK158 or genetic knockdown of PFKFB3 significantly prevents the tumor formation of SCLC cells in vivo." (PMID 35804016, 2022). "PFKFB3 knockdown inhibited cancer cell proliferation in vitro and attenuated tumor growth/metastasis in animal models." (PMID 35961977, 2022). "It was demonstrated that PFKFB3 is predominantly expressed on CD14+CD68+ monocyte-derived macrophages that massively infiltrate tumor tissue." (PMID 36733385, 2022). "In conclusion, our data suggest that PFKFB3-5 mediates growth inhibiting effects in vitro, while PFKFB3-4 exerts the opposite effect on tumor cell growth." (PMID 34234350, 2021). "Tumor vessels of PFKFB3-silenced mice have been observed to contain considerable CD31+ laminin+ staining in the basement membrane, indicating vessel maturation." (PMID 34831136, 2021). "The significance of PFKFB3 level has been reported in cancer cells but also in tumor-related cells such as cancer stem cells." (PMID 33671514, 2021). "Overall, PFKFB3 provides tumor cells with a reversible alternative that can provide protection against self-destruction and ensure cell survival simply by switching from biosynthesis to cellular redox." (PMID 34831136, 2021).
tumor (continued). "Although the regulatory role of post‐translational modification of PFKFB3 in tumor regulation is of great importance, the mechanism of PFKFB3 protein stability in BC is still unclear." (PMID 33931981, 2021). "Based on the regulatory function of PFKFB3 in glycolysis and cellular metabolism, an increasing number of studies have focused on investigating its role in tumor growth." (PMID 33420377, 2021). "The expression of PFKFB3 is the highest in human tumor cells in situ, and its enzyme activity, which is about 700 times of phosphatase, is conducive to the synthesis of F-2 and 6-BP, the most potent stimulants for glycolysis." (PMID 34612136, 2021). "For example, inhibition of a key component of the glycolytic pathway, 6-phosphofructo-2-kinase/fructose-2,6-biphosphatase 3 (PFKFB3), results in anti-tumour activity in mesothelioma, with death occurring at least in part via the induction of ER stress." (PMID 34226685, 2021). "Recent findings indicate that inhibition of PFKFB3, either with chemical inhibitors or genetic silencing, reduces the glycolytic rate and suppresses tumor cell proliferation." (PMID 33420377, 2021). "Compared to oxaliplatin-treated mice, combination of C. tropicalis up-regulated the mRNA expression of pivotal glycolysis-related enzymes in tumor tissues, including Pgam1, Pkm2, Ldha and Pfkfb3." (PMID 34345205, 2021). "A recent study showed that blockade of the glycolytic activator PFKFB3 in tumor endothelial cells reduced cancer cell invasion, intravasation, and metastasis, and improved the effect of chemotherapy on primary and metastatic tumors." (PMID 34907156, 2021). "PFKFB3-1 constitutes the best studied and most abundant PFKFB splice variant in tumor cells known to promote tumorigenic progression." (PMID 34234350, 2021). "For instance, inhibiting PFKFB3 in hyper-glycolytic tumor endothelial cells has beneficial effects, such as tumor vessel normalization, reduced metastasis and improved chemotherapy." (PMID 33672100, 2021). "PFKFB3 kinase activity is known to increase the rate of glycolysis and promote the proliferation, migration, invasion, and growth of tumor cells." (PMID 34907156, 2021). "Meanwhile, previous studies reported that tumor angiogenesis can be promoted by PFKFB3-mediated glycolysis, and the production of VEGF, the most powerful pro-angiogenic growth factor, is increased." (PMID 34079757, 2021). "Blockade of PFKFB3 improves vessel maturation and perfusion, thereby reducing tumor cell invasion, intravasation, and metastasis and enhancing the efficiency of chemotherapy on tumors." (PMID 33546224, 2021). "Several small molecule inhibitors of PFKFB3 have been developed, although their application to cancer treatment has been limited since tumor cells have developed unique survival strategies to antagonize inhibition of glucose metabolism." (PMID 34234350, 2021). "LncRNAs CamK-A, BRCA4, and AGPG wires up NF-kB, Hippo and Hedgehog, and PFKFB3 glycolytic enzyme complexes, respectively, to remodel glucose metabolism and tumor microenvironment, promoting tumor development." (PMID 33868368, 2021). "Silencing the expression of PFKFB3 in BC can reduce the glycolytic flux, inhibit proliferation of cancer cells, and induce tumor cell apoptosis." (PMID 33931981, 2021). "Recently, PFKFB3 has been shown to be a promising target, not only due to its crucial involvement in glycolysis, but also because of its ability to induce tumor vessel normalization and to lead to drug sensitization." (PMID 33671096, 2021). "Combining currently used chemotherapeutics (conventional or tumor pathway-specific agents) with PFKFB3 or PFKFB4 inhibitors is expected to enrich the range of treatment options." (PMID 33671514, 2021). "Targeted treatment of alterations characteristic of these neoplasms combined with the inhibition of PFKFB3 enhanced the apoptotic pathway and induced cytotoxicity." (PMID 33671514, 2021).
tumor (continued). "It has been shown that genetic or pharmacological inhibition on PFKFB3 attenuates glycolytic flux and induces prosurvival autophagy in colon and gynecological cancer in vitro and in vivo, thus limiting tumor’s sensitivity to chemotherapy." (PMID 34359849, 2021). "6-Phosphofructo-2-kinase/fructose-2,6-bisphosphatase 3 (PFKFB3), a glycolytic enzyme, is overexpressed in a variety of human cancers and plays important roles in promoting tumor cell growth." (PMID 33420377, 2021). "The essential role of glycolytic enzymes like HK2 and PFKFB3 in maintaining the high glycolytic tumor phenotypes has been reported in recent years." (PMID 32841217, 2020). "Inhibition of PFKFB3 in ECs decreased tumor metastasis by inducing the normalization of the tumor vessels." (PMID 32375250, 2020). "As expected, our data demonstrated that PFKFB3 is significantly increased after BEV monotherapy despite delayed tumor growth and increased survival." (PMID 32641990, 2020). "In contrast, the addition of 3PO reduces the expression of BEV-induced PFKFB3 and greatly lowers tumor growth and extends survival." (PMID 32641990, 2020). "Findings regarding the differences in the normal EC and tumor EC indicate an up-regulated expression of glycolytic gene PFKFB3 and hence prove that tumor EC are highly glycolytic." (PMID 32012744, 2020). "PFKFB3 is a key glycolysis regulator that has been proposed to act as a tumor promoter by accentuating cell migration and invasion." (PMID 33324631, 2020). "PFKFB3, the key rate-limiting enzyme, leads to enhanced glycolysis, which is essential for tumor cell survival." (PMID 33324631, 2020). "Such a pathway was compromised by high level of PFKFB3 O-GlcNAcylation in tumor cells contributing to cell cycle progression." (PMID 32060258, 2020). "In experiments performed in mice with tumor, inhibition of PFKFB3 in EC reduced glycolysis, and subsequently reduced lactate level." (PMID 32012744, 2020). "PFKFB3 inhibition with 3PO effectively suppressed tumour growth in combination with multi-kinase inhibitors nintedanib and sunitinib in a mouse model of breast cancer." (PMID 33092283, 2020). "TECs exhibit upregulated glycolysis due to elevated expression of 6-phosphofructo-2-kinase/fructose-2,6-biphosphatase 3 (PFKFB3), which regulates proliferation and migration during tumor angiogenesis." (PMID 33469537, 2020). "By AMPK-dependent phosphorylation of PFKFB3, the metabolic pattern in tumor cells is switched from oxidative respiration to glycolysis." (PMID 32631382, 2020). "This contributes to the high glycolytic rate of hypoxic tumor cells and has made PFKFB3 a target for pharmaceutical interventions." (PMID 33083755, 2020). "For example, inhibition of the glycolytic activator, 6-phosphofructo-2-kinase/fructose-2,6-bisphosphatase 3 (PFKFB3), normalizes tumor vasculature by tightening endothelial cell junctions." (PMID 32645038, 2020). "Previous studies have reported that over-expression of GLUT1, PFKFB3, and GAPDH in endothelial cells is a common feature of tumor-activated endothelial cells, and the inhibition of PFKFB3 leads to vessel normalization and reduces metastasis." (PMID 32244977, 2020). "3PO, a glycolysis inhibitor targeting PFKFB3, can inhibit the glycolysis of nintedanib- and sunitinib-resistant tumor cells via inducing cell-cycle arrest and apoptosis, and thus promote the therapeutic efficacy of chemo- and radio-therapy." (PMID 31122265, 2019). "HK2 gene was significantly and positively correlated with tumor size, whereas PFKFB3 was significantly and positively correlated with COL1A1, COL3A1, and HAS2 genes in TN." (PMID 31428701, 2019). "Among them, PFKFB3 is regarded as the major player contributing to elevated glycolysis in tumor cells due to its unique high kinase/phosphatase activity ratio and the inducible nature of this gene under hypoxia and inflammatory conditions." (PMID 31569510, 2019).
tumor (continued). "miR‐488 suppresses glycolysis and then inhibits tumor proliferation through downregulation of PFKFB3 expression." (PMID 31410981, 2019). "We further experimentally confirmed that miR‐488 directly binds to the 3′‐UTR of the 6‐phosphofructo‐2‐kinase/fructose‐2,6‐bisphosphatase 3 (PFKFB3) gene, thereby regulating tumor proliferation and glycolysis in PCa." (PMID 31410981, 2019). "PFKFB3 is consistently overexpressed in many tumor cells, and knockdown of PFKFB3 promotes apoptosis of tumor cells." (PMID 30606113, 2019). "PFKFB3 expression was further analyzed by quantitative polymerase chain reaction (qPCR) and Western blot in paired tumor (T) and peritumor (P) liver tissues from 12 patients with HCC." (PMID 29559632, 2018). "Tumors implanted in mice with complete PFKFB3 deletion grow more slowly due to reduced tumor perfusion." (PMID 30255018, 2018). "In a study of head and neck squamous cell carcinoma, blocking PFKFB3 suppressed tumor growth and metastasis mediated by suppressing glycolysis." (PMID 29559632, 2018). "It is currently unclear how the activity of PFKFB3 is stimulated to facilitate tumor growth and survival." (PMID 29410405, 2018). "JAK2V617F and active STAT5 overexpress PFKFB3 and PFKFB3 silencing reduces cell growth under normoxic and hypoxic conditions and prevents tumor formation." (PMID 30234009, 2018). "Inhibition of PFKFB3 by chemical inhibitors or genetic silence dramatically reduces glycolytic flux, Ras-driven transformation and tumor growth in athymic mice." (PMID 29410405, 2018). "The effect of PFKFB3 inhibition on the tumor vasculature is dependent though on the degree of inhibition." (PMID 30255018, 2018). "Tumor endothelial cells are also characterized by a hyper-glycolytic metabolism, and blockade of the glycolytic enzyme PFKFB3 was able to reduce cancer cell invasion and metastasis." (PMID 28971272, 2018). "The combination of cisplatin and PFKFB3 inhibition by PFK15 was more potent to inhibit tumor growth than each single treatment, suggesting a possible benefit of combining PFKFB3 inhibitors with cisplatin therapy." (PMID 29410405, 2018). "Inhibition of PFKFB3 with chemical inhibitors or genetic silence reduces glycolysis rate and suppresses tumor cell proliferation." (PMID 29410405, 2018). "In breast and ovarian cancer cell line models, the PFKFB3 inhibitor 3-PO suppresses glycolytic flux and tumor growth." (PMID 29559632, 2018). "The results showed that PFKFB3 expression was higher in tumor tissues compared with paired peritumor liver tissues." (PMID 29559632, 2018). "In tumor models, inhibition of PFKFB3 impairs nuclear factor kappa B (NF-κB) transcriptional activity in endothelial cells by targeting the phosphorylation of p65 and IκBα, which in turn decreases CAM expression." (PMID 29719532, 2018). "Recently, an article reported that targeting PFKFB3 in ECs significantly impeded metastasis by normalizing tumor vessels and improved the delivery and efficacy of chemotherapy." (PMID 30234009, 2018). "Our findings reveal a mechanism for cells to stimulate glycolysis to protect from DNA damage and potentially suggest a therapeutic strategy to sensitize tumor cells to genotoxic agents by targeting PFKFB3." (PMID 29410405, 2018). "Recently, upregulation of PFKFB3, a key regulator of ECs glycolysis, was shown to lead to the development of immature and dysfunctional vasculature in tumor angiogenesis." (PMID 28785263, 2017). "At the same time, heightened glycolysis in tumor cells is PFKFB3-dependent and inhibition of the same enzymes was shown to reduce glucose uptake and proliferation of human hematopoietic and adenomatous cancer cell lines." (PMID 28785263, 2017). "PFKFB3 inhibitors have been proven to work as regulators for glycolysis and metabolism, which can be expected to suppress tumor cells in vivo and in vitro." (PMID 28977989, 2017).